RPN2 (ribophorin II)
Diseases named in the same sentence as RPN2 in open-access papers (continued):
Sharing a sentence is not in itself a finding about the gene and the disease.
osteosarcoma (5 papers, 2014 to 2022). A usually aggressive malignant bone-forming mesenchymal neoplasm, predominantly affecting adolescents and young adults. "Therefore, we plan to further investigate the molecular mechanisms underlying RPN2 upregulation and the interactions of N-linked glycosylation with invasion-related molecules with RPN2 in osteosarcoma cells." (PMID 25181275, 2014). "Mice bearing RPN2-silenced highly metastatic osteosarcoma xenografts showed reduced tumor growth and lung metastasis, and survived longer than mice bearing control tumor xenografts." (PMID 25181275, 2014). "Immunohistochemical evaluation of 35 osteosarcoma patient biopsies revealed that RPN2 was moderately to highly expressed in all specimens, and higher RPN2 mRNA expression was significantly correlated with poor prognosis." (PMID 25181275, 2014). "We found that RPN2 expression also regulates the invasiveness of osteosarcoma cells, representing a novel function of RPN2." (PMID 25181275, 2014). "In this context, we have shown that RNA interference for RPN2 suppresses cell proliferation, sphere formation ability, and invasiveness, and increases the sensitivity of osteosarcoma cells to a wide range of chemotherapeutic drugs in vitro." (PMID 25181275, 2014). "To confirm the effect of RPN2 mRNA expression in osteosarcoma cells by treatment with currently used drugs, we performed qRT-PCR for 143B cells after doxorubicin treatment." (PMID 25181275, 2014). "In this study of osteosarcoma cells, we demonstrated that silencing of RPN2 increased cell sensitivity to doxorubicin, methotrexate, and docetaxel." (PMID 25181275, 2014). "To evaluate the functional effects of regulating RPN2 expression in osteosarcoma cells, we first confirmed the expression of RPN2 mRNA in several osteosarcoma cell lines." (PMID 25181275, 2014). "All the mice were evaluated for survival, and 143B-shRPN2-bearing mice showed longer survival than 143B-shNC-bearing mice (log-rank test, P = 0.020), suggesting that decreased RPN2 expression provided a survival advantage on osteosarcoma-bearing mice." (PMID 25181275, 2014). "Our human study demonstrated that high expression of RPN2 in biopsy samples of osteosarcoma was significantly correlated with patient prognosis." (PMID 25181275, 2014). "We then tested the tumor cell responses to a wide range of drugs that have been used for treatment of osteosarcoma, and found that RPN2 silencing increased the sensitivity to doxorubicin, methotrexate, and docetaxel." (PMID 25181275, 2014). "In summary, we have shown that the RPN2 gene is moderately to strongly expressed in all osteosarcomas, and that higher RPN2 expression is significantly correlated with clinical metastasis and poor patient survival." (PMID 25181275, 2014). "Taken together, our data suggest that RPN2 silencing contributes to regulation of lethal osteosarcoma phenotypes and could be a novel target for RNAi-based therapeutics against osteosarcoma." (PMID 25181275, 2014). "To investigate whether lethal phenotypes of osteosarcoma could be reduced by regulating the expression of RPN2, we conducted a study of RNAi-induced RPN2 knockdown in highly metastatic human osteosarcoma cells." (PMID 25181275, 2014). "Here, we report the clinical and functional correlations of RPN2 expression in osteosarcoma." (PMID 25181275, 2014). "Furthermore, silencing of RPN2 contributes to reduction of cell proliferation, sphere formation, and invasiveness, and sensitizes osteosarcoma cells to standard chemotherapeutic regimens, thus providing a survival advantage on osteosarcoma-bearing mice." (PMID 25181275, 2014). "We considered that the correlation between high-RPN2 expression in biopsy samples and prognosis might have been due to the metastatic expression of osteosarcoma, since RPN2 expression was significantly correlated with clinical metastasis." (PMID 25181275, 2014).
osteosarcoma (continued). "Notably, RPN2 silencing inhibited tumor growth as well as lung metastasis formation, leading to a survival advantage of osteosarcoma-bearing mice." (PMID 25181275, 2014). "In addition, we investigated whether the level of RPN2 expression affected cell proliferation, drug sensitivity, sphere formation ability, and cell invasion in osteosarcoma in vitro, as well as tumor growth and metastatic ability in vivo." (PMID 25181275, 2014). "In this study, we examined RPN2 expression using immunohistochemical staining and quantitative real-time polymerase chain reaction (qRT-PCR) of pretreatment biopsy samples from patients with osteosarcoma, and evaluated the correlation between RPN2 expression and clinicopathological features." (PMID 25181275, 2014). "As a result, we found higher expression of RPN2 in 143B, a highly metastatic osteosarcoma cell line, than in SaOS2 or HOS, which are poorly metastatic osteosarcoma cell lines." (PMID 25181275, 2014).
bladder cancer (4 papers, 2022 to 2024). "Highly expressed RPN2 was found in bladder cancers, and higher RPN2 expression was associated with patients’ tumor T stage, lymph node metastasis, and pathological degree of tumor differentiation." (PMID 35156537, 2022). "Meanwhile, we found high expression of RPN2 in bladder cancer tissues in the TCGA, GSE19915 and GSE13507 datasets." (PMID 37108067, 2023). "Meanwhile, overexpression of the downstream target gene, RPN2, could rescue the effect of reduced METTL3/YTHDF1 expression on bladder cancer cells." (PMID 37108067, 2023).
glioblastoma (4 papers, 2022 to 2024). The most malignant astrocytic tumor (WHO grade IV). "The lncRNA WEE2-AS1 can act as a scaffold for RPN2, and the resulting WEE2-AS1/RPN2 complex activates the PI3K-AKT signaling pathways to promote the progression of glioblastoma." (PMID 37915034, 2023). "In a different study, the forced expression of miR-181c temozolomide sensitivity by Ribophorin II (RPN2) inhibition mediated apoptosis induction in glioblastoma cells." (PMID 36676955, 2022). "In terms of downregulated genes in glioblastoma, we found NDRG4, SERPINA3, RPN2, VIM, and TIMP1 to be differentially the most downregulated genes." (PMID 38769480, 2024).
head and neck squamous cell carcinoma (3 papers, 2015 to 2022). A squamous cell carcinoma that arises from any of the following anatomic sites: lip and oral cavity, nasal cavity, paranasal sinuses, pharynx, larynx, and salivary glands. "We observed that RPN2 is also highly altered in head and neck squamous cell carcinoma (HNSCC), as well as lung squamous cell carcinoma, consistent with previously published studies." (PMID 26388988, 2015). "Our results suggest that RPN2 might be a predictive marker for treatment response to induction chemotherapy with TPF in patients with p16-negative locally advanced head and neck squamous cell carcinoma." (PMID 34575229, 2021). "A recent study revealed that elevated RPN2 expression was related to a poor response to induction chemotherapy in locally advanced p-16 negative head and neck squamous cell carcinoma." (PMID 35156537, 2022). "Thus, this study aims to evaluate the relationship between RPN2 and the effect of treatment using induction therapy with TPF for locally advanced head and neck squamous cell carcinoma." (PMID 34575229, 2021). "However, the relationship between RPN2 expression and treatment response to chemotherapy with TPF in patients with locally advanced head and neck squamous cell carcinoma remains unclear." (PMID 34575229, 2021). "This study aims to evaluate the relationship between human ribophorin II (RPN2) and the effect of treatment using induction therapy with docetaxel, cisplatin, and fluorouracil (TPF) for p-16 negative locally advanced head and neck squamous cell carcinoma (HNSCC)." (PMID 34575229, 2021).
hepatocellular carcinoma (3 papers, 2020 to 2022). A malignant tumor that arises from hepatocytes. "Huang L found that RPN2 promotes metastasis of hepatocellular carcinoma cell and inhibits autophagy via STAT3 (signal transducer and activator of transcription-3) and NF-κB pathways." (PMID 33692975, 2021).
liver cancer (3 papers, 2021 to 2023). An epithelial or non-epithelial malignant neoplasm that arises from the liver. "RPN2 is located in the rough endoplasmic reticulum and regulates proliferation, invasion and drug resistance in breast, colon, esophageal and liver cancers." (PMID 37108067, 2023). "RPN2 promotes liver cancer metastasis and reduces autophagy by regulating STAT3 and NF-κB signaling pathways." (PMID 33613755, 2021). "RPN2 has been manifested to repress autophagy in liver cancer." (PMID 33937013, 2021).
lung carcinoma (3 papers, 2015 to 2023). "In our study, RPN2 silencing by siRNA in lung cancer cells selectively regulated the expression of two principal genes involved in intrinsic apoptosis control." (PMID 25595901, 2015). "Remarkably, we found that the intrinsic apoptosis signaling pathway is the mechanism of cell death induced by RPN2 silencing in lung cancer cells." (PMID 25595901, 2015). "Together, these results indicate that RPN2 silencing confers therapeutic and survival advantages to lung cancer cells in vivo." (PMID 25595901, 2015). "In this study, we also show that RPN2 modulates the metastatic phenotypes in recurrent NSCLC patients as well as the cell invasion ability of lung cancer cells." (PMID 25595901, 2015). "To evaluate the mode of cell death induced by RPN2 silencing in lung cancer cells, we performed assays for apoptosis using Hoechst staining and western blot analyses in these cells after RPN2 siRNA transfection." (PMID 25595901, 2015). "To further understand the potential biological significance of a high RPN2 expression level during lung cancer progression, we evaluated the correlation between the RPN2 expression profile and relapse-free survival in the cohort study." (PMID 25595901, 2015). "Histological analyses also revealed that RPN2 silencing represses the tumor growth of this lung cancer cell line." (PMID 25595901, 2015). "Moreover, RPN2 silencing by shRNAs repressed lung tumor growth and sensitized the lung cancer cells to cisplatin treatment." (PMID 29632637, 2018). "To further understand the potential biological significance and clinical relevance of RPN2 expression in lung cancer progression, we evaluated the correlation between RPN2 expression and survival in tumor specimens from 177 NSCLC patients who experienced recurrence after curative resection." (PMID 25595901, 2015). "Furthermore, RPN2 silencing by siRNAs suppresses cell proliferation and invasiveness and increases the sensitivity of lung cancer cells to chemotherapeutic drugs in vitro." (PMID 25595901, 2015). "Recently, we reported that a novel RNAi therapeutic platform against RPN2 demonstrated an efficient inhibition of lung tumor growth, but we have not yet revealed the molecular functions and clinical relevance of RPN2 in lung cancer." (PMID 25595901, 2015). "We speculate that RPN2 confers lung cancer cell growth and various lethal phenotypes by modulating anti-apoptotic intrinsic signaling." (PMID 25595901, 2015). "To investigate the functional effects of regulating RPN2 in NSCLC cells, we first verified the expression of RPN2 mRNA in various lung cancer cell lines." (PMID 25595901, 2015). "Furthermore, the authors reported that a naked, unmodified novel RNAi agent, such as ribophorin II (RPN2-PnkRNA), used as a therapeutic target for lung cancer, plays a key role in the inhibition of tumour growth without any significant toxicity." (PMID 37374157, 2023). "Notably, RPN2 silencing by shRNAs repressed lung tumor growth and sensitized the lung cancer cells to CDDP treatment, which led to the longer survival of lung cancer-bearing mice." (PMID 25595901, 2015).
lymph node metastasis (2 papers, 2013 to 2018). "Analysed by GO database and KEGG pathways database, eIF3a and RPN2 which were low-expression in regional lymph node metastasis tissues were the most frequently selected genes affecting regional lymph node metastasis in our study and validated by qRT-PCR." (PMID 24386425, 2013).
myeloid malignancies (2 papers, 2015 to 2020). "The RPN2 gene has been localized to chromosome 20ql2–13.1, a region that is often compromised in patients who develop malignant myeloid tumors." (PMID 32404045, 2020).
pancreatic cancer (2 papers, 2015 to 2021). "In addition to its association with myeloid disorders, RPN2 has been demonstrated to be a prognostic marker of human breast and pancreatic cancers." (PMID 25789057, 2015). "RPN2 is also highly expressed in the CD24+CD44+ cancer stem-like cells of pancreatic cancer." (PMID 33692975, 2021). "Ribophorin II (RPN2) has been demonstrated to be a prognostic marker of human cancer, including breast and pancreatic cancers." (PMID 25789057, 2015).
antiphospholipid syndrome (1 paper, 2021). A disorder caused by the presence of autoantibodies directed against phospholipids, causing a hypercoaguable state, which may result in blood clots, stroke, heart attack, and in women, significant pregnancy-related complications, including miscarriage and still birth. "Fujieda suggested that RPN2 is involved in the pathophysiology of thrombosis in patients with antiphospholipid syndrome (APS)." (PMID 33692975, 2021).
basal cell carcinoma (1 paper, 2022). A carcinoma involving the basal cells. "The signaling pathways impacted by RPN2 mainly include basal cell carcinoma, the complement and coagulation cascades, DNA replication and protein export." (PMID 36439123, 2022).
colorectal tumor (1 paper, 2017). "Clinicopathological analysis showed that the overexpression of RPN2 and EGFR was positively correlated with colorectal tumor size." (PMID 29069815, 2017).
congenital disorder of glycosylation (1 paper, 2013). Congenital disorder of glycosylation (CDG) is a fast growing group of inborn errors of metabolism characterized by defective activity of enzymes that participate in glycosylation (modification of proteins and other macromolecules by adding and processing of oligosaccharide side chains). "Mutations in RPN2 have been shown to belong to a group of inherited human disorders called, Congenital Disorders of Glycosylation (CDG)." (PMID 24130834, 2013).
glaucoma (1 paper, 2013). Increased pressure in the eyeball due to obstruction of the outflow of aqueous humor. "In addition, an association of central corneal thickness, a quantitative risk factor for glaucoma, to a SNP in the ribophorin II gene was identified." (PMID 23536807, 2013).
head and neck cancer (1 paper, 2019). A primary or metastatic malignant neoplasm affecting the head and neck. "Interestingly, tumor cells with decreased proteasome activity were shown to be radioresistant, and the reduced expression of Rpn2 in tumors was associated with worse prognosis in radiotherapy-treated patients with head and neck cancer." (PMID 31456945, 2019).
Kawasaki disease (1 paper, 2021). A rare inflammatory disease characterized by an acute febrile, systemic, self-limiting, medium-vessel vasculitis primarily affecting children. "We speculate that the RPN2/JAK1/STAT3 axis could be a potential therapeutic target in Kawasaki disease because of its known effect on inflammatory reactions." (PMID 33692975, 2021). "The effect of five SNPs that showed to be the most statistically associated with the Kawasaki disease in this study was evaluated, this includes: rs12037447 in non-coding sequence and rs146732504 in KIF25, rs151078858 in PTPRJ, rs55723436 in SPECC1L, rs6094136 in RPN2 genes." (PMID 33692975, 2021).
left ventricular hypertrophy (1 paper, 2012). Enlargement of the LEFT VENTRICLE of the heart. "Increased expression of the representative subunits of 19S (RPN2 and RPT11) and 20S (α6) have also been reported in the subendocarium of the canine model of left ventricular hypertrophy." (PMID 23166589, 2012).
mesenchymal neoplasms (1 paper, 2014). "However, the function and correlation of RPN2 expression with the clinical features of other malignancies, including mesenchymal neoplasms, remains to be elucidated." (PMID 25181275, 2014).
metastatic disease (1 paper, 2014). "Univariate analysis revealed a significant correlation between high-RPN2 expression and the presence of metastasis at initial diagnosis (P = 0.039), and we found that four patients who had metastatic disease at the time of initial diagnosis were all ranked in the high-RPN2 group." (PMID 25181275, 2014).
pancreatic diseases (1 paper, 2024). "Dysregulation of RPN2 and its associated pathways can contribute to the development of various pancreatic diseases via defective insulin production, impacting glucose homeostasis." (PMID 39000422, 2024).
rheumatoid arthritis (1 paper, 2025). A chronic, systemic autoimmune disorder characterized by inflammation in the synovial membranes and articular surfaces. "In rheumatoid arthritis, RPN2 expression is significantly upregulated in peripheral blood mononuclear cells and PHA-activated primary T lymphocytes, indicating its involvement in immune cell activation, proliferation, and apoptosis." (PMID 40963867, 2025).
senile osteoporosis (1 paper, 2020). "Our findings also offer an innovative aim for therapy of senile osteoporosis and evidence to prompt additional investigation of the interaction between RPN2 and the JAK1/STAT3 pathway in hBMSC osteogenic differentiation." (PMID 31743606, 2020).